TLR4 (toll like receptor 4)
Diseases named in the same sentence as TLR4 in open-access papers (continued):
Sharing a sentence is not in itself a finding about the gene and the disease.
COVID-19 (continued). "In COVID-19, the ectodomain of the SARS-CoV-2 spike protein has been reported to stimulate TLR4,91,92 though other reports suggest lipopolysaccharide or other contaminants may be driving immune activation." (PMID 39876559, 2025). "In this study, we used mRNA-seq data from the peripheral blood of COVID-19 patients to identify six COVID-19 severe immune characteristic genes (FPR1, FCGR2A, TLR4, S100A12, CXCL1, and L TF), and found neutrophils to be the critical immune cells in COVID-19 severe disease." (PMID 38674681, 2024). "Research has demonstrated that SARS-CoV-2 S protein binds to TLR4 with greater affinity than to ACE2, leading to aberrant signaling that contributes to the hyperinflammatory response seen in COVID-19 patients." (PMID 39744674, 2024). "On the other hand, activation of TLRs such as TLR2, TLR4, and TLR7/8 leads to the release of proinflammatory cytokines by cells, a phenomenon which studies have shown to largely determine the development of complications in COVID-19." (PMID 39457048, 2024). "Furthermore, TLR4 along with its downstream mediators, including CD14, MyD88, and TRAF6 among others, have been observed to increase in COVID-19 patients." (PMID 38287815, 2024). "TLR4 is a key signalling pathway in acute lung inflammation, and TLR7/8 also plays a key role in inflammatory signalling in response to viral infections in the lung including severe influenza and COVID-19." (PMID 39137914, 2024). "Moreover, we show II) that TLR4 is the most abundantly expressed TLR in the human lung, and III) that its expression is merely restricted to AMΦ in severe COVID-19." (PMID 38034686, 2023). "Likewise, TLR4 and its downstream elements (including Myd88, IRAK1 and TRAF6, and NF-κB - dependent genes) were significantly upregulated in PBMCs from 20 human COVID-19 patients." (PMID 38439942, 2023). "Additionally, TLR4 and ABCA1 showed significant upregulation specifically in CD16+ monocytes of COVID-19 patients, suggesting their potential involvement in the immune response during COVID-19." (PMID 38022594, 2023). "Importantly, TLR4 is critically involved in LPS- and virus-induced ALI, including COVID-19-induced ALI." (PMID 37344492, 2023). "The dysregulation of TLR4 and ABCA1 may provide novel insights into the immune dysregulation and inflammatory response seen in COVID-19 and AMI cases." (PMID 38022594, 2023). "Furthermore, we identify TLR4 and ABCA1 as potential contributors to the immune-related pathogenesis of COVID-19 with AMI." (PMID 38022594, 2023). "Therefore, TLR4 and ABCA1 were determined to be the most significantly correlated genes in common with COVID-19 and AMI." (PMID 38022594, 2023). "In addition, the expression of TLR1, TLR4, TLR5, and TLR8 was significantly elevated in patients with severe or critical COVID-19, and the expression of TLR7 was increased in patients with moderate or critical COVID-19." (PMID 37310504, 2023). "Gegen Qinlian pill (GQP) is a traditional Chinese medicine, which can inhibit toll-like receptor 4 (TLR4)/nuclear factor κB (NF-κB) signaling, has good anti-inflammatory activity, has a good effect on the treatment of COVID-19, and has shown anti-thrombotic potential." (PMID 37841272, 2023). "Then, regression analyses indicated that 9 prognostic genes (including ANPEP, OAS1, SCGB1A1, HLA‐A, NPPB, FGB, CCL2, TLR4, and SERPINE1) might play important roles in quercetin for treating UCEC/COVID-19." (PMID 36969077, 2023). "Nevertheless, our study showed a trend to TLR-4 up-regulation in lungs of a subgroup patients with lethal COVID-19, when compared to the control group of SARS-CoV-2 negative lungs." (PMID 37686069, 2023). "Neuro-inflammation triggered by SARS-CoV-2 spike protein, which was injected intra-cerebroventricularly (non-sterile infection model), which binds to TLR-4, has been discussed to mediate long-term cognitive impairment after COVID-19." (PMID 37508529, 2023).
COVID-19 (continued). "The Cox regression analyses suggested that 9 prognostic genes (ANPEP, OAS1, SCGB1A1, HLA‐A, NPPB, FGB, CCL2, TLR4, and SERPINE1) might act critical roles in the treatment of UCEC/COVID-19." (PMID 36969077, 2023). "TLR2 and TLR4 sense viral proteins, and the expression levels of molecules related to the TLR2- and TLR4-inflammatory signaling molecules are upregulated in in COVID-19 patients, which suggest the involvement of TLR2 and TLR4 signaling in the induction of pathological inflammation during COVID-19." (PMID 35832809, 2022). "Moreover, we identified seven possible pharmacological targets of vitamin D against COVID-19/HCC, including HMOX1, MB, TLR4, ALB, TTR, ACTA1 and RBP4." (PMID 36275701, 2022). "Therefore, the analysis of the genotypes of TLR2, TLR3, TLR4, TLR6, TLR7, TLR8, and TLR9 is important for the study of COVID-19." (PMID 35327350, 2022). "Our study concluded that impaired renal and cardiac biomarkers might be attributed to increased expression levels of TLR2, TLR4, ACE2, and NRP-1 mRNA in both moderate and severe COVID-19 patients." (PMID 35891270, 2022). "Blocking of TLR4, JAK2 and STAT3 signaling could prevent excessive production of calprotectin by Dok3-/- neutrophils, revealing new targets for potential COVID-19 therapy." (PMID 36172386, 2022). "Notably, ACE2, a known critical target of COVID-19 infecting renal cells, was engaged in the PPI network by interacting with TLR4." (PMID 36052061, 2022). "TLR4 activation, aberrant TLR4 signaling, and hyperinflammation may explain SARS-CoV-2-induced myocarditis and multiple-organ injury in COVID-19 patients." (PMID 36274722, 2022). "Increased expression of HIF-1α mRNA has also been reported in myeloid blood cells from critically ill COVID-19 patients, along with the expression of other genes, TLR2 and TLR4, which could be involved in SARS-CoV-2 sensing." (PMID 34835108, 2021). "Zheng and colleagues reanalyzed the expression of MyD88 and TLRs in patients with different severity grades of COVID-19 using a public dataset and found that the expression of MyD88, TLR1, TLR2, TLR4, TLR5, TLR8, and TLR9 was increased in patients with severe to critical illness." (PMID 34834939, 2021). "Various TLR4 modulators, such as EB05 (NCT04401475), Eritoran (NCT02735707), Naltrexone (NCT04604704, NCT04604678), Curcumin (NCT04382040), and Berberine (NCT04479202) are undergoing clinical trials for COVID-19." (PMID 34834939, 2021). "Interestingly, TLR4 and TLR5, which are both downregulated in COVID-19 are also essential for the germinal center response as they activate the NF-κB signaling pathway via MYD88." (PMID 33950285, 2021). "Innate immune receptor activation or inactivation has not been studied extensively for severe COVID-19-associated ARDS, but consistent evidence exists for the activation of TLR4, TLR7 and NLRP3." (PMID 33672738, 2021). "Other TLRs (TLR1, TLR4, TLR5) were also found to be downregulated in COVID-19." (PMID 33950285, 2021). "Furthermore, the binding of SARS-CoV-2 PAMPs to the extracellular domain of human TLR1, TLR4, and TLR6 seems to be crucial for COVID-19 immunopathogenesis." (PMID 34281186, 2021). "Although no drugs to block TLR4 signaling have been approved, dexamethasone, an anti-inflammatory steroid, is now expected to be effective in treating critically ill patients with COVID-19." (PMID 33644468, 2021). "TLR4, one of the important inflammatory signal receptors of the pathogen recognition receptors family (PRR), plays a critical role in the activation of immune system as influenza virus and COVID-19 invasion." (PMID 33349263, 2020). "In contrast, TLR4 may contribute to the cytokine release (e.g., TNF) induced by HMGB1 in immune cells, which is also related to COVID-19." (PMID 33313438, 2020). "Furthermore, a negative correlation was observed between miRNA-20a and TLR4 levels, suggesting potential therapeutic or predictive implications for these two biomarkers in COVID-19 management." (PMID 39149604, 2024).
COVID-19 (continued). "Considering the vital role of the TLR4–NF-κB signaling pathway in mediating the synergistic stimulation of spike protein and IL-2 in inducing inflammatory cytokines, this pathway presents a promising target for preventing or reducing CRS in patients with COVID-19." (PMID 39359733, 2024). "Therefore, the combination of TLR4 inhibitor and TNF-α neutralizing antibody may represent a promising therapeutic strategy in treating CRS in patients of COVID-19 and other syndromes, such as CAR-T cell anti-tumor therapy, where CRS is a common side effect." (PMID 39359733, 2024). "Yet, the knowledge about immunological effects of OxPAPC remains controversial, as other studies have indicated that it may function as a TLR4 and TLR2 agonist both in vitro and in vivo, overall limiting its potential as drug to inhibit hyperinflammation in severe COVID-19 [19,]." (PMID 38034686, 2023). "No genetic causal link between COVID-19 and AMI and dysregulated TLR4 and ABCA1 may be responsible for the development of immune and inflammatory responses in COVID-19 patients with AMI." (PMID 38022594, 2023). "We concluded that, miR-20a, is a potential biomarker of COVID-19 severity and blockade of IL-10 and TLR4 may constitute a novel therapy for COVID-19 patients." (PMID 36864077, 2023). "In conclusion, low secretion of IL-8 was observed upon stimulation with TLR2, TLR4, TLR7/8, TLR9, and NOD2 agonists by the blood cells of COVID-19 patients at hospital admission and was restored after two weeks of hospitalization, which may be a contributing factor to immunosuppression." (PMID 37189696, 2023). "However, the inflammatory response in COVID-19 still shares some common signatures with the inflammatory response in LPS-induced RAW264.7 cells, among which the most typical are TLR4, NF-κB, and other signaling pathways and their corresponding cytokines (including IL-6, TNF, IL-1β, etc.)." (PMID 35669076, 2022). "Interestingly, a set of patients with severe COVID-19, originally included as a negative control, showed high-activation levels of TLR4 at both time points." (PMID 36230982, 2022). "Employing the molecular docking and systems network pharmacological strategies to uncover the molecular mechanisms, anti-SARS-CoV2/COVID-19 effects of these potential bioactive molecules could be shown to be altered by key bioactives and some corresponding genes such as MAPK14, ACE, TLR4, and MAPK8." (PMID 36144690, 2022). "Consequently, an interaction between TLR4 and SARS-CoV2 spike proteins could be the reason behind the COVID-19 immunopathological expression." (PMID 36144690, 2022). "Moreover, other studies on SARS-CoV-2 have revealed the pathological role of TLR4 and TLR7/8 in excessive inflammatory response in COVID-19 patients as it leads to the formation of neutrophil extracellular traps (NETs) and the activation of inflammasomes, leading to acute lung injury." (PMID 35832809, 2022). "Thus, LXs through inhibition of TLR-4/MyD88, may reduce SARS-CoV-2-induced hyperinflammation and cytokine storm in COVID-19." (PMID 36114383, 2022). "The binding of the spike protein to TLR4 may be involved in SARS-CoV-2 entry into human cells and/or initiating the cytokine storm that affects multiple organs, a serious complication which occurs in the severe stages of COVID-19." (PMID 33505220, 2021). "Therefore, in obese patients with increased expression of TLR4, the AT, which is already inflamed, makes a favorable environment for SARS-CoV-2-TLR4 interaction, exacerbating the pro-inflammatory cytokine production and increasing the severity of COVID-19." (PMID 34564326, 2021). "However, due to increased expression of TLR4 and activating DAMPs of TLR2 and 4 in patients with COVID-19, Dectin-1 may participate in cross-communication with TLRs during S protein and DAMP identification and stimulation." (PMID 33498183, 2021).
COVID-19 (continued). "Nitrite attenuated the pro- and anti-inflammatory response induced by the S protein without interfering with the activation of TLR4 and antioxidant enzyme expression, raising the possibility that nitrite could have potential as a coadjutant in the treatment of COVID-19." (PMID 38474248, 2024). "In summary, the response of TLR4 and of TLR2 to SARS-CoV-2 may switch the anti-viral response of the lung from the release of type I IFNs to an exaggerated synthesis of pro-inflammatory mediators, explaining at least in part the hyperinflammation observed in severe COVID-19." (PMID 38034686, 2023). "Hence, through the negative modulation of the TLR4/MyD88 pathway, irisin could improve the condition of patients with COVID-19 and their outcomes." (PMID 35784579, 2022). "Further, we identified seven overlapping genes of vitamin D against HCC and COVID-19 using the network pharmacology approach, and the anti-COVID-19/HCC effects of vitamin D may be modulated by these molecules or genes, including HMOX1, MB, TLR4, ALB, TTR, ACTA1 and RBP4." (PMID 36275701, 2022). "Similarly, dendritic cells (DCs) from COVID-19 patients had weaker baseline expression of maturation markers CD83 (MMR 0.75) and HLA-DR (MMR 0.59, p = 0.018), along with a trend toward reduced expression of pattern recognition receptors (PRR) CD284/TLR4 (MMR 0.29) and Dectin-1 (MMR 0.62)." (PMID 36052094, 2022). "The highest expression levels are found for Cathepsin L, followed by TLR4/MD-2 and TLR2 on macrophages and endothelial cells, whereas ~10fold lower expression levels are seen for TLR1, 6, and 7, which may correlate with the different pathophysiological relevance in COVID-19, as discussed later." (PMID 35682644, 2022). "Extracellular vesicles (EVs) from the plasma of COVID-19 patients have been shown to contribute to neutrophil extracellular trap formation through mechanisms independent of ACE2 and TLR4." (PMID 41322987, 2025). "Severity and disease progression in patients with COVID-19 was shown to correlate with the expression of MyD88, i.e., a key adaptor molecule in TLR-signaling, and the expression of TLR1, TLR2, TLR4, TLR5, TLR8 and TLR9 (but not TLR3)." (PMID 38791489, 2024). "Lastly, the increased expression of TLR4, but not ABCA1, was validated in clinical blood samples from COVID-19 patients with AMI." (PMID 38022594, 2023). "By contrast, expression of TLR4, TLR5, TLR6, and TLR7 was not altered in COVID-19-derived monocytes." (PMID 37310504, 2023). "Computationally, the spike protein binds stronger to TLR4 than ACE2, and if there is a secondary bacterial infection in COVID-19 (which accounted for 10% of ICU patients in one study), TLR4 would also be activated by gram-negative bacterial LPS." (PMID 33505220, 2021). "TLR1, TLR4, TLR5, TLR8, and TLR9 expression levels were also significantly elevated in severe and critical COVID-19 patients; however, TLR3 expression was not correlated with the development of COVID-19, and an increased expression of TLR7 was observed only in patients with moderate COVID-19." (PMID 34835108, 2021).
Stroke (212 papers, 2009 to 2026). Sudden impairment of blood flow to a part of the brain due to occlusion or rupture of an artery to the brain. "The conversion of microglia from M1 to M2 can suppress post-stroke neuronal loss and reduce neurological deficits, and this phenomenon is related to TLR4/NFκB cascade." (PMID 40289983, 2025). "In other rodent models, neuroinflammation caused by LPS and stroke was lowered with glycyrrhizin treatment by reducing HMGB1-mediated TLR4-NF-κB activation." (PMID 38550920, 2024). "In ethnic Chinese in Taiwan, TLR4 C119A polymorphism is linked to stroke severity; Asp299Gly polymorphism implicated in protection from AD does not affect stroke severity." (PMID 38299364, 2024). "Research indicates TLR4’s involvement in recognizing Damage-Associated Molecular Patterns (DAMPs) post-stroke." (PMID 38887610, 2024). "Loss of TLR4 increases the level of alternative Neutrophils and is associated with neuroprotection after stroke." (PMID 38154101, 2023). "Overall, the in vitro results indicate that the inhibitory effect of the TA gel on proinflammatory microglial polarization is associated with suppressing the activation of the TLR4/NF-κB signaling pathway after stroke." (PMID 37908012, 2023). "TLR2 and TLR4 are associated with the production of inflammatory cytokines by monocytes, TLR4 expression is associated with infarct volume, stroke severity, and functional outcome." (PMID 37452512, 2023). "Platelet TLR4 has been found to play a critical role in stroke injury in a NET-dependent manner, and upregulation of TLR4 is associated with higher inflammation and poorer outcomes in stroke." (PMID 36892020, 2023). "Toll-like receptor signaling pathway is important in mediating the formation of immune system after stroke, and previous animal experiments have shown that TLR2 or TLR4 deficient mice have less brain tissue damage after stroke than wild-type mice." (PMID 35722467, 2022). "TLR2 and TLR4 signaling appears to be important in controlling pathogenic immune responses after stroke, and estrogen, progesterone, and vitamin D3 all regulate TLR2 and TLR4 signaling, making them therapeutic options for stroke treatment." (PMID 36212660, 2022). "Meanwhile, several clinical studies also noted the critical role of TLRs in a stroke patient, particularly the involvement of TLR4 polymorphism in terms of stroke prevalence." (PMID 31134076, 2019). "Developing drugs targeting TLR4 has become promising for stroke and multiple pathologies in which it is implicated." (PMID 30384431, 2018). "TLR4 deficiency is neuroprotective in ischemic stroke in mice, and increased TLR4 expression is associated with more severe stroke in patients." (PMID 29766045, 2018). "Recent evidences have linked TLR4-signaling in multiple neurodegenerative conditions such as AD, PD, stroke, and TBI." (PMID 28127491, 2017). "Clinical studies have also examined the role of TLRs in stroke patients, including those that focus on the association of TLR-4 polymorphisms with the prevalence of stroke." (PMID 28115020, 2017). "There are at least 11 TLR proteins in mammals, and TLR4 is implicated in the pathogenesis of stroke-related inflammation." (PMID 27143001, 2016). "Combined we show that stroke (pMCAO) triggers central and peripheral galectin-3 release causing enteric neuronal loss through a TLR4 mediated mechanism involving TAK1 and AMPK." (PMID 27612206, 2016). "In the ischemic injury models, MMP9 activity was detected in endothelial cells, astrocytes, and neurons, and HMGB1 released during stroke was implicated in activation of MMP9 via TLR4 signaling." (PMID 25879213, 2015). "Neurons from both TLR2 knockout and TLR4-deficient mice were protected against ischemia, and the amount of brain damage and neurological deficits caused by a stroke were significantly lesser in mice deficient in TLR2 or TLR4 compared with control mice." (PMID 25886362, 2015).